RN7SKP113 (RN7SK pseudogene 113)
Gene: Miscellaneous RNA gene on chromosome 4 (4,920,770 to 4,921,064, reverse strand). Ensembl gene ENSG00000200761.
Homologues: Orthologues: chimpanzee 7SK (96% identical), guinea pig 7SK (72% identical), mouse Gm56285 (70% identical). Paralogues in human: 7SK (74% identical), RN7SKP9 (74% identical), RN7SKP184 (74% identical), RN7SKP176 (73% identical), RN7SKP255 (73% identical), RN7SKP189 (73% identical), RN7SKP25 (73% identical), RN7SKP173 (73% identical), RN7SKP217 (73% identical), RN7SKP28 (73% identical), RN7SKP50 (73% identical), RN7SKP124 (72% identical), and 284 more.